ZNF471 (zinc finger protein 471)
Diseases named in the same sentence as ZNF471 in open-access papers (continued):
Sharing a sentence is not in itself a finding about the gene and the disease.
lymph node metastasis (2 papers, 2021 to 2024). "The methylation level of ZNF471 was significantly correlated with clinicopathological characteristics such as stage, grade, lymph node metastasis, and histological type." (PMID 33566221, 2021). "In addition, the results of TCGA database showed that the methylation level of ZNF471 in renal cancer tissues was positively correlated with high clinical stage, lymph node metastasis, and high pathological grade in patients with RCC, but not with patient sex or age." (PMID 38169650, 2024).
non-small cell lung carcinoma (2 papers, 2020 to 2021). A group of at least three distinct histological types of lung cancer, including non-small cell squamous cell carcinoma, adenocarcinoma, and large cell carcinoma. "It has been reported that miR-942-5p promotes tumor migration and invasion via ZNF471 in non-small cell lung cancer (NSCLC)." (PMID 34322152, 2021).
adenoma (1 paper, 2023). A neoplasm arising from the epithelium. "B Receiver operator curve (ROC) analysis for ZNF471 predicting aberrant methylation in adenoma." (PMID 37779184, 2023).
breast tumors (1 paper, 2020). "Ectopic expression of ZNF471 substantially inhibited breast tumor cell growth in vitro and in vivo, arrested cell cycle at S phase, and promoted cell apoptosis, as well as suppressed metastasis." (PMID 33203470, 2020).
colon cancer (1 paper, 2023). "Interestingly, four genes that were originally highly expressed in the high SOCS3 expression group in colon cancer became low expressed after lung metastasis, including TTC40, PCDHA2, SP3P and ZNF471." (PMID 37025997, 2023).
colorectal adenoma (1 paper, 2023). An adenoma that arises from the colon or rectum. "Our results showed that all the genes of ZNF471, SND1, SPOCK1, FBLIM1, and OTX1 methylation with the area under receiver operating curve (ROC) more than 0.90 were significantly high in the colorectal adenoma and CRC compared with the normal group." (PMID 37779184, 2023). "Based on the results of the methylation chip of Illumina Infinium 450K detection and bioinformatic analysis, five hypermethylated genes, ZNF471, SND1, SPOCK1, FBLIM1, and OTX1, were selected for further investigation in the colorectal adenoma, CRC, and control normal tissues in our study." (PMID 37779184, 2023).
esophageal tumor (1 paper, 2020). "We examined ZNF471 expression by real-time RT-PCR in paired esophageal tumor and adjacent non-tumor tissues." (PMID 32089740, 2020).
gastric tumors (1 paper, 2018). "Higher protein expression of ZNF471 was detected in 6 out of 10 paired gastric tumors than adjacent tissues (P = 0.05)." (PMID 29610526, 2018). "Collectively, these findings suggested that ZNF471 is a novel gastric tumor suppressor which functions by transcriptional inhibition of its oncogenic targets, TFAP2A and PLS3." (PMID 29610526, 2018). "In addition, the mRNA level of ZNF471 was significantly decreased in gastric tumor tissues compared with tumor adjacent tissues (n = 56, P = 0.0001)." (PMID 29610526, 2018).
leukemia (1 paper, 2021). A malignant (clonal) hematologic disorder, involving hematopoietic stem cells and characterized by the presence of primitive or atypical myeloid or lymphoid cells in the bone marrow and the blood. "Among the other genes with strong correlations between DNA methylation and gene expression, aberrant DNA methylation and downregulation of FKBP9, CA8, MSC, TRPC6, ZNF492, ZNF229, and ZNF471 genes in leukemia patients are reported here for the first time." (PMID 34575904, 2021).
lung adenocarcinoma (1 paper, 2020). A carcinoma that arises from the lung and is characterized by the presence of malignant glandular epithelial cells. "In addition, LIFR-AS1 is positively correlated with ZNF471 mRNA in lung adenocarcinoma, according to TCGA datasets." (PMID 32489316, 2020).
Obesity (1 paper, 2022). Accumulation of substantial excess body fat. "As a result, we found GWAS signals relevant to obesity around rs2870099 as follows: rs34863160 (ZNF470), rs11670527 (DUXA, ZNF264), and rs16987303 (ZNF471) were associated with birth weight, BMI, and height, respectively." (PMID 36276968, 2022).
oral squamous cell carcinoma (1 paper, 2021). "We had previously reported hypermethylation of ZNF471 in oral squamous cell carcinoma of the tongue." (PMID 33566221, 2021).
renal carcinoma (1 paper, 2024). A carcinoma arising from the epithelium of the renal parenchyma or the renal pelvis. "The results showed that the invasion and metastasis abilities of renal cancer cells in the ZNF471 overexpression group were significantly lower than those of renal cancer cells in the control group." (PMID 38169650, 2024). "Through CCK-8 assays and plate colony formation assays, we found that the proliferation ability of renal cancer cells in the ZNF471 knockdown group was significantly higher than that of renal cancer cells in the control group." (PMID 38169650, 2024). "In contrast, knocking down ZNF471 promoted the growth of renal cancer cells and induced their metastasis." (PMID 38169650, 2024). "Through CCK-8 assays and plate colony formation assays, we found that the proliferation ability of renal cancer cells in the ZNF471 overexpression group was significantly lower than that of renal cancer cells in the control group." (PMID 38169650, 2024). "Subsequently, we used RT-PCR and methylation-specific PCR to quantify the expression and methylation levels of ZNF471 in renal cancer cell lines and found that the expression of ZNF471 in renal cancer cell lines was lower than that in normal cell lines." (PMID 38169650, 2024). "Compared with the ZNF471 group, the number of apoptotic renal cancer cells in ZNF471+siBANP group was reduced." (PMID 38169650, 2024). "By using immunofluorescence techniques, we found that ZNF471 was localized primarily in the nucleus in renal cancer cells." (PMID 38169650, 2024). "In our study, we found that the methylation level of ZNF471 in renal cancer tissues was positively correlated with high clinical stage, but not with pathological grade, tumor size, sex and age in patients with RCC." (PMID 38169650, 2024). "In this study, we found that overexpression of ZNF471 significantly inhibited the proliferation and metastasis of renal cancer cells, and induced apoptosis and cell cycle arrest in renal cancer cells." (PMID 38169650, 2024). "The results showed that compared with the control group, the ZNF471 knockdown group of renal cancer cell lines exhibited the highest knockdown efficiency after transfection with siRNA for 24 h." (PMID 38169650, 2024). "The methylation level of ZNF471 in the renal cancer cell line was higher than that in the normal cell line." (PMID 38169650, 2024). "We first used data from the TCGA database to analyse the methylation of ZNF471 in RCC, and the results showed that the methylation level of ZNF471 in renal carcinoma tissues was significantly higher than that in adjacent normal tissues." (PMID 38169650, 2024). "By western blot analysis, we found that the expression of ZNF471 in adjacent normal tissues was higher than that in renal cancer tissues." (PMID 38169650, 2024). "In this study, we explored the potential molecular mechanism of ZNF471's inhibitory role in renal cancer by transcriptome sequencing." (PMID 38169650, 2024). "The aim of this study was to explore the role of abnormal methylation of ZNF471 in the development of renal carcinoma." (PMID 38169650, 2024). "In this study, we first used the TCGA database to analyse the expression of ZNF471 in renal cancer tissues, and the results showed that the expression of ZNF471 in most tumour tissues was significantly lower than that in adjacent normal tissues, with renal cancer tissues exhibiting this pattern." (PMID 38169650, 2024). "In addition, compared with Vector+siBANP group, the number of apoptotic renal cancer cells in ZNF471+siBANP group was significantly increased." (PMID 38169650, 2024). "Therefore, to investigate the effect of ZNF471 on the invasion and metastasis of renal carcinoma cells, wound healing assays and Transwell migration assays were performed." (PMID 38169650, 2024). "Furthermore, the expression of ZNF471 in renal carcinoma tissues was negatively correlated with tumour stage and grade in patients with renal carcinoma." (PMID 38169650, 2024).
renal carcinoma (continued). "Next, to further test whether ZNF471 can inhibit renal cancer metastasis in vivo, ZNF471-overexpressing and empty vector-expressing ACHN cells were injected into the tail vein of NCG mice, and lung colonization was analysed 30 days later." (PMID 38169650, 2024). "To further verify the inhibitory effects of ZNF471 on renal cancer cells, we used a siRNA targeting ZNF471 to knock down the expression of ZNF471 in renal cancer cell lines, and then we used qRT-PCR to evaluate the knockdown efficiency after transfection for 24 h and 48 h." (PMID 38169650, 2024). "In summary, these results suggested that ZNF471 could interact with BANP in renal cancer cells and inactivate PI3K/AKT/mTOR signalling, thus further suppressing the malignant phenotype of RCC cells." (PMID 38169650, 2024). "To verify the biological function of ZNF471 in renal cancer, we transfected the pcDNA3.1-ZNF471 expressing plasmid into renal cancer cell lines (786-O, ACHN, and caki-1), and then, the ZNF471 overexpression efficiency was analysed by qRT-PCR after transfection for 24 h, 48 h and 72 h." (PMID 38169650, 2024). "In conclusion, these results suggested that the low expression of ZNF471 in renal carcinoma might be due to promoter CpG hypermethylation." (PMID 38169650, 2024). "Therefore, ZNF471 could suppress the malignant phenotype of renal cancer by inhibiting the activation of the PI3K/AKT/mTOR signalling pathway." (PMID 38169650, 2024). "In addition, ZNF471 reversed EMT to inhibit the invasion of renal cancer cells." (PMID 38169650, 2024). "In addition, the results of the wound healing assay and Transwell migration assay showed that the invasion and metastasis abilities of renal cancer cells in the ZNF471 knockdown group were significantly increased compared with those of renal cancer cells in the control group." (PMID 38169650, 2024). "In addition, by immunohistochemical analysis, we found that the expression of ZNF471 in normal kidney tissues was higher than that in renal cancer tissues and that the expression of ZNF471 decreased with increasing postoperative pathological stage of the tumour." (PMID 38169650, 2024). "To further explore whether BANP could inhibit the proliferation of renal cancer cells by affecting the cell cycle, we conducted cell cycle analysis, and the results showed that compared with Vector group, the progression of cell cycle was significantly inhibited in ZNF471 group." (PMID 38169650, 2024). "On the other hand, we could propose new methods using ZNF471 agonists, taking advantage of ZNF471's tumour suppressor role in RCC, for renal cancer therapy." (PMID 38169650, 2024). "Using The Human Protein Atlas database, we found that the protein expression level of ZNF471 in renal cancer tissues was lower than that in adjacent normal tissues." (PMID 38169650, 2024). "To verify the biological function of BANP in renal cancer, we transfected a BANP-specific siRNA into renal cancer cells (786-O and ACHN) stably transfected with ZNF471 to knock down the expression of BANP, and then qRT-PCR was used to determine the knockdown efficiency after transfection." (PMID 38169650, 2024). "Furthermore, the expression of ZNF471 in renal carcinoma tissues was negatively correlated with clinical stage and pathological grade in patients with renal carcinoma but was not correlated with patient sex or age." (PMID 38169650, 2024).
renal cell carcinoma (1 paper, 2024). "Finally, we elucidated the underlying molecular mechanisms of ZNF471 in renal cell carcinoma by transcriptome sequencing, bioinformatics analysis and molecular biology experiments." (PMID 38169650, 2024). "Next, we investigated the effects of ZNF471 on the proliferation, metastasis, cell cycle progression, and apoptosis of renal cell carcinoma cells by cell biology experiments." (PMID 38169650, 2024). "The results of the cell biology experiments showed that ZNF471 could significantly inhibit the proliferation, migration and cell cycle progression of renal cell carcinoma cells and promote apoptosis in these cells." (PMID 38169650, 2024). "However, the role of ZNF471 in renal cell carcinoma is currently unclear." (PMID 38169650, 2024). "However, the function and mechanism of ZNF471 in renal cell carcinoma remain unclear." (PMID 38169650, 2024).
tumor (18 papers, 2014 to 2026). "These ZNF471-regulated target genes reveal the underlying mechanisms of tumor suppression by ZNF471 in ESCC cells." (PMID 32089740, 2020). "The tumour-specific promoter methylation of ZNF471 might be a candidate diagnostic and therapeutic biomarker for RCC." (PMID 38169650, 2024). "Genes like DAPK1, LRPPRC, RAB6C, and ZNF471 are found to be the targets of promoter hypermethylation that leads to the altered gene expression patterns that help in growth of tumours." (PMID 41487403, 2026). "As a member of the KRAB-ZNF family, ZNF471 plays an important role in the progression of various tumours." (PMID 38169650, 2024). "The results of HE and IHC staining showed that the number of tumour cells with robust nuclear fragmentation was increased in xenografts with ZNF471 overexpression, accompanied by a decrease in Ki-67 staining." (PMID 38169650, 2024). "Four weeks after injection, the volume and weight of tumours in nude mice were significantly smaller in the ZNF471-overexpressing group than in the control group." (PMID 38169650, 2024). "The upregulated genes including GAB3, SLC8A1, KCNMA1, and ZNF471 following CFP1 knockdown, were expressed at low levels in tumor tissues and were associated with favorable prognosis of LUAD patients." (PMID 37735441, 2023). "Mechanistically, ectopic expression of ZNF471 significantly inhibited the growth, proliferation, migration, and invasion of SiHa and CaSki cells in vitro and tumor growth in vivo." (PMID 33566221, 2021). "The suppressive role of ZNF471 in ESCC is mediated through the regulation of various tumor suppressors, such as MAPK10/JNK3 and protocadherin (PCDH) genes that are involved in apoptosis induction and cell adhesion, respectively." (PMID 33672287, 2021). "ZNF471 expression significantly suppressed in vivo tumor growth in nude mice grafted with SiHa and CaSki cells." (PMID 33566221, 2021). "The sensitivity and specificity of the ZNF471 hypermethylation for squamous intraepithelial lesion (SIL) vs tumor and normal vs tumor was above 85% with AUC of 0.937." (PMID 33566221, 2021). "Among the identified zinc finger proteins in our study, ZNF471 functions as a tumor suppressor in several cancers and is frequently hypermethylated in tumor tissues." (PMID 34944472, 2021). "The promoter CpG site methylation of ZNF471 was significantly different among cancer types and tumor grades." (PMID 33566221, 2021). "The available experimental data indicate that ZNF471 acts as a tumor suppressor in these cancers through its involvement in the regulation of cell apoptosis, migration, invasion, and proliferation." (PMID 33672287, 2021). "The anchorage-dependent assay showed the tumor growth suppressive function of ZNF471 in SiHa and CaSki cells (P<0.005)." (PMID 33566221, 2021). "Here, we showed evidence for distinct methylation marks conserved across clusters of specific CpG sites in ZNF471 within various clinical diagnostic categories such as SIL and SCC, thus facilitating tumor typing." (PMID 33566221, 2021). "H & E staining of tumor tissue cryosection (5 μm thickness) revealed visible histological differences between the tumors developed from mice receiving ZNF471 expressing cells and control SiHa cells." (PMID 33566221, 2021). "ZNF471 exerted its tumor suppressor function by reducing the EMT, inhibiting cell stemness, and blocking AKT and Wnt/β-catenin signaling." (PMID 33203470, 2020). "Tumor cells with frequent nuclear fragmentation were primarily observed in xenografts with ZNF471 expression, along with increases in MAPK10 staining, decreases in Ki-67 staining and increases in cell apoptosis." (PMID 32089740, 2020). "ZNF471 stably transfected ESCC cells showed adherence and contacts with each other; however, vector control cells exhibited a scattered pattern, thus indicating that ZNF471 is likely to be involved in tumor cell epithelial mesenchymal transition (EMT)." (PMID 32089740, 2020).